PPARG (peroxisome proliferator activated receptor gamma)
Diseases named in the same sentence as PPARG in open-access papers (continued):
Sharing a sentence is not in itself a finding about the gene and the disease.
Obesity (continued). "In addition, L-carnitine supplementation has been shown to improve insulin resistance and restore mitochondrial function in high-fat diet-induced obesity models by inducing autophagy through peroxisome proliferator-activated receptor gamma (PPARγ) activation." (PMID 41373407, 2025). "The mechanisms underlying adropin's role in obesity are still under investigation, and it may exert its effects via multiple signaling pathways, including AMPK, PPARγ, and Sirtuin 1 (SIRT1)." (PMID 41211169, 2025). "L-carnitine may improve insulin resistance by inducing autophagy through PPARγ and removing dysfunctional mitochondria in the skeletal muscle of a high-fat-diet-induced rodent model of obesity." (PMID 40589780, 2025). "The epigenetic modulation exerted by breastfeeding seems to also affect other genes involved in energy metabolism, such as fat mass and obesity-associated (FTO) gene, Retinoid X Receptor Alpha (RXRA), and human peroxisome proliferator-activated receptor gamma (PPAR-γ) gene." (PMID 40004988, 2025). "Atractylodes lancea extract has been reported to attenuate obesity and improve glucose tolerance in high-fat diet-induced obese mice, likely through modulation of PPAR-γ (peroxisome proliferator-activated receptor gamma) activity, which plays a key role in insulin sensitivity and lipid metabolism." (PMID 41029678, 2025). "In addition, kimchi combined with red yeast rice has demonstrated an anti-obesity effect by modulating biomarker expression in the liver X receptor α (LXRα) and peroxisome proliferator-activated receptor γ (PPARγ) pathways." (PMID 41189663, 2025). "The anti - obesity effect of LJ3402 is mediated via the PPARγ pathway." (PMID 40822402, 2025). "In this study, through a combined multi‐omics, pharmacological, and pharmacokinetic approaches, it is found that BBR‐induced obesity‐specific DILI is primarily through the potentiation of peroxisome proliferator‐activated receptor gamma (PPARγ) signaling pathways." (PMID 39611414, 2025). "In our cohort, participants with T2DM initially met criteria for obesity (BMI > 30), but later declined below this threshold, which may reflect early PPARG upregulation followed by later downregulation or improved diabetes management." (PMID 41282094, 2025). "Therefore, regulating PPARγ expression and the type of fatty acids consumed can play a key role in preventing or progressing obesity‐related metabolic disorders." (PMID 40968591, 2025). "Furthermore, the anti-obesity effect of PRLE was mechanistically associated with the downregulation of key transcription factors, including PPARγ and C/EBPα, underscoring its distinct action through the inhibition of adipogenesis." (PMID 41155630, 2025). "Consequently, the inhibition of PPARγ and C/EBPα represents a potential strategy for the prevention and treatment of obesity." (PMID 41155164, 2025). "Decreased expression of MTFP1 was linked to increased expression of PPARG (Peroxisome Proliferator-Activated Receptor Gamma) and LPL (Lipoprotein Lipase), two known obesity-related genes important for adipogenesis, lipid metabolism, and ultimately energy homeostasis." (PMID 40216759, 2025). "The dysregulation of AMP-activated protein kinase (AMPK), sterol regulatory element-binding protein-1c (SREBP-1c), and peroxisome proliferator-activated receptor gamma (PPARγ) plays a central role in metabolic dysfunction and disease progression, including obesity, insulin resistance, and cancer." (PMID 40282189, 2025). "The hepatic expression of PPARγ is elevated in patients with obesity and MASLD." (PMID 40985048, 2025). "A study investigating its anti-obesity potential in 3T3-L1 adipocytes showed that harpagoside inhibited tumor necrosis factor-α (TNF-α)-induced adipokine expression by activating of peroxisome proliferator-activated receptor gamma (PPAR-γ)." (PMID 41226163, 2025).
Obesity (continued). "However, newer derivatives are being developed to act as dual agonists of both PPARα and PPARγ, offering potential benefits in treating conditions such as obesity and diabetic cardiomyopathy." (PMID 40732311, 2025). "Recent studies on PPARG signaling examine connections between obesity, cancer, and the vitamin D/VDR system, introducing new research hypotheses in this area." (PMID 40334012, 2025). "However, biases related to genetic predispositions must be considered, as genes such as FTO, MC4R, PPARG, and TMEM18 are associated with obesity and metabolic disorders, especially in European populations." (PMID 40827223, 2025). "Thus, CNOT4 positively regulates transcriptional activity of PPARγ during adipocyte differentiation in obesity." (PMID 40424271, 2025). "Specific strains such as LJ3402 demonstrate anti-obesity effects by enhancing mitochondrial function and promoting thermogenesis via the PPARγ pathway, while BFE6154 exerts cholesterol-lowering activity by modulating key hepatic and intestinal genes involved in lipid absorption and metabolism." (PMID 40822402, 2025). "Furthermore, obesity triggers inflammation in adipose tissue, which increases the expression of aromatase in adipocytes through Peroxisome Proliferator-Activated Receptor Gamma (PPARγ) and pro-inflammatory factors." (PMID 40564033, 2025). "PPARγ induces adipocyte hypertrophy and insulin resistance in diet-induced obesity." (PMID 41438090, 2025). "Studies have shown that moderate inhibition of PPARG activity can prevent insulin resistance and obesity induced by high-fat diets, while PPARG antagonists can improve insulin sensitivity and promote the browning of white adipose tissue, potentially offering a safer therapeutic approach." (PMID 40564064, 2025). "Tlcd3b may play a role in obesity as ceramides inhibit adipogenesis, through interaction with the obesity‐related gene Pparγ." (PMID 39988938, 2025). "This study suggests that PPARγ may facilitate a futile cycle between circadian disruption and obesity development." (PMID 40149950, 2025). "Additionally, the impact of omega‐3 FAs on PPARγ activity further highlights the complexity of dietary lipid interactions in obesity and metabolic disorders." (PMID 40968591, 2025). "PPARγ and C/EBPα are crucial in regulating fat cell development and metabolism in obesity." (PMID 41306340, 2025). "Further research is warranted to elucidate the causal relationship between GDF10-mediated inhibition of PPARγ and cholesterol metabolism independent of obesity." (PMID 38245533, 2024). "Regulating PPARG expression may impact adipocyte development and fatty acid storage, thereby treating obesity on a cellular scale." (PMID 38794679, 2024). "Indeed, emerging evidence suggests a role of specific lipid mediators in the perturbations of puberty in conditions of early-obesity, while hypothalamic PPARγ seems to modulate part of reproductive responses to high-fat diet in mice." (PMID 39290326, 2024). "However, Gynostemma pentaphyllum, a TCM that is generally used to treat hypercholesterolemia and inflammation, has been demonstrated to reduce obesity and obesity-related inflammation by down-regulating PPARγ signaling pathway." (PMID 38699583, 2024). "To investigate whether ANXA1 affected mice obesity via PPARγ in vivo, we treated HFD-fed Anxa1AKO mice with GW9662 (intraperitoneal injection every other day at a dose of 1 mg/kg for 16 weeks)." (PMID 39174522, 2024). "Additionally, PPARG has been involved in the pathology of many diseases, including obesity, diabetes, atherosclerosis, and cancer." (PMID 39114361, 2024). "PGZ, a PPARγ agonist, improves a variety of metabolic syndromes related to diabetes and obesity." (PMID 39334695, 2024).
Obesity (continued). "In this study, we assessed the nutritional components of unripe citrus peel and pressed juices, as well as their anti-obesity potential through the modulation of adipocyte differentiation and the expression of adipogenesis-related genes, specifically PPARγ and C/EBPα, in 3T3-L1 preadipocytes." (PMID 38693048, 2024). "The interest in AKT1 and PPARG proteins for anti-obesity purposes is substantial due to their close association with the PI3K/Akt and PPAR signaling pathways, which play crucial roles in obesity-related processes." (PMID 39409084, 2024). "Therefore, activation of PPARγ in adipocyte by the thiazolidinedione (TZD) class of insulin-sensitizing drugs (TZDs) can improve obesity and insulin sensitivity." (PMID 38332049, 2024). "With regards to T2D and obesity treatments, this underscores the importance of identifying and characterizing new regulatory cofactors of PPARγ, particularly ones such as ZFP407, which impacts both transcriptional regulatory networks as well as adipocyte development and homeostasis." (PMID 38781157, 2024). "However, under conditions of obesity, these transcription factors, PPARγ and C/EBPα, not only enhance insulin-mediated glucose uptake but also contribute to increased FFA production." (PMID 39683533, 2024). "Additionally, miR-130 was found to be downregulated in obesity and reported as modulating 5 lncRNAs controlling PPARγ cell signaling." (PMID 38668382, 2024). "Peroxisome proliferator-activated gamma (PPARγ) is a ligand-activated member of the nuclear hormone receptor superfamily and controls adipocyte differentiation and function, and thus becomes a classic target to treat obesity-related disorders." (PMID 38332049, 2024). "Furthermore, KA decreased the adipose tissue size and downregulated the expression of genes related to insulin resistance in obesity, including leptin, PPARγ, and adiponectin." (PMID 38655315, 2024). "PPARγ is a nuclear receptor transcription factor that plays a key role in adipogenesis and is a major therapeutic target for various diseases including obesity, dyslipidemia, type 2 diabetes mellitus, neurodegenerative disorders, and cancers." (PMID 38473849, 2024). "Although a previous study indicates that PAR2 accelerates adipocyte differentiation, our recent data did not observe any difference in the expression of adipogenesis marker PPARγ between patients who are lean and patients with obesity or between WT and Par2–/– mice with high fat diet feeding." (PMID 38973609, 2024). "In brown adipose tissue, METTL3 deletion decreases the m6A modification and expression of the PR domain containing 16 (PRDM16), uncoupling protein 1 (UCP-1), and peroxisome proliferator-activated receptor gamma (PPARG) and thereby promotes high-fat diet-induced obesity." (PMID 38560499, 2024). "A PPARγ-driven targeted therapeutical approach requires selective ligands that activate the receptor, resulting in beneficial effects in fighting diabetes and obesity." (PMID 39199386, 2024). "PEITC supplementation was able to decrease the expression levels of NF-κB, LOX-1, and COX-2, ameliorating obesity-induced inflammation via mTOR/PPARγ/AMPK signaling (mammalian target of rapamycin/peroxisome proliferator-activated receptor gamma/adenosine-monophosphate activated-protein kinase)." (PMID 38542669, 2024). "The expression of LPL, a protein responsible for breaking the triglycerides from lipoprotein into FFA, and its transcriptional regulator PPARγ mRNA levels are also reduced in omental AT from pregnant women with obesity compared with lean pregnant women on the day of partum." (PMID 39083072, 2024). "Our findings shed light on how PPARγ agonists promote adipose tissue plasticity in obesity." (PMID 39579770, 2024).
Obesity (continued). "CKD, however, is a complex disease and our animal model does not entirely reflect the clinical setting present in patients with CKD in terms of co-morbidities such as diabetes or obesity as well as possible interference with additional medication besides PPARγ agonists." (PMID 39175545, 2024). "Due to the inclusion of PPARG as a key target for the three categories of molecules and considering the importance of PPARG in treating obesity, we performed molecular docking to screen the affinity of active small molecules in Nelumbo nucifera leaves for PPARG." (PMID 39744140, 2024). "In addition, PPARγ activation during obesity depends on a number of other factors, including polyunsaturated fatty acids (PUFAs) and prostaglandins (e.g., J2 or D2)." (PMID 39683397, 2024). "Peroxisome proliferator-activated receptor gamma (PPAR-γ) and sterol regulatory element-binding protein-1c (SREBP-1c) are key transcription factors that regulate lipid metabolism and are implicated in the link between obesity and HCC." (PMID 37834153, 2023). "Despite substantial research on how quercetin affects obesity, its impact on PPARγ and adipokines is unknown." (PMID 37513932, 2023). "PPARγ is involved in several diseases, such as diabetes, atherosclerosis, obesity, and cancer." (PMID 36672947, 2023). "Moreover, our discoveries provide a promising strategy for guiding the development of novel PPARγ agonists for the treatment of obesity and related metabolic disorders." (PMID 36329235, 2023). "Protective effects of the drugs may be through correlations between SIRT-1/adipokines/IGF-1 and PPARγ, improving the cross-talk between insulin resistance, obesity markers, liver dysfunction, and TNF-α." (PMID 36991247, 2023). "By uncovering the role of PPARγ acetylation in regulating metabolic rhythms, our study presents the possibility that approaches to manipulate PPARγ acetylation in a circadian‐dependent manner may restore healthy metabolic oscillations in obesity and aging." (PMID 36394167, 2023). "Additionally, factors related to adipose tissue, including resistin, peroxisome proliferator-activated receptor gamma, and peptide YY, are believed to participate in the detrimental influence of obesity on bone health." (PMID 37571429, 2023). "V supplementation in mice with high-fat-diet-induced obesity could inhibit preadipocyte differentiation and adipogenesis through the downregulation of the adipogenic transcription factors PPARγ and C/EBPα and their target genes in 3 T3-L1 adipocytes." (PMID 36771259, 2023). "PPARγ might be the potential target for Rb1 in obesity-related insulin resistance, which would be a therapy for early T2D treatment." (PMID 37049846, 2023). "Here, we show that a PPARγ/long noncoding RNA (lncRNA) axis integrates canonical and noncanonical thermogenesis to restrain white adipose tissue heat dissipation during thermoneutrality and diet-induced obesity." (PMID 37909330, 2023). "Analysis of the ToxCast database revealed positive associations between BPS and PPARγ activity, and the authors proposed that BPS-activation of PPARγ as a mechanism for the observed relationship of BPS exposure with increased adipogenesis and obesity." (PMID 37529602, 2023). "In conclusion, Rb1 could affect the secretion and release of inflammatory factors through the important target of PPARγ, regulate the activation of macrophages, and further inhibit the occurrence of insulin resistance in obesity." (PMID 37049846, 2023). "Another study demonstrated that knockdown of AACS in vivo decreases peroxisome proliferator-activated receptor γ (PPARγ) and CCAAT/enhancer binding protein α (C/EBP α), which can enhance bone resorption and have a critical role in relationship between obesity and bone loss." (PMID 38075675, 2023). "However, most studies on vitamin D‐regulating action of PPARγ on obesity have focused on adipocyte differentiation." (PMID 37823117, 2023).
Obesity (continued). "However, in chronic inflammation like that in obesity, PPARγ expression can be downregulated, and the protein is degraded." (PMID 36986146, 2023). "However, one study showed that the PPARγ agonist rosiglitazone increased Serpine1 expression in a diet-induced obesity model, and therefore the role of PAI-1 is unclear." (PMID 37886997, 2023). "Blocking PPARγ phosphorylation at Thr166 prevents obesity‐related metabolic dysfunction." (PMID 37143582, 2023). "This expansion in size impairs the function of PPARγ and limits the adipogenetic turnover of mesenchymal cells to adipocytes, while it favors mechanical-stress-induced hypoxia, the low-grade inflammation of obesity, and insulin resistance." (PMID 36986146, 2023). "In a study using human muscle satellite cells, it was found that rosiglitazone promoted adipogenic differentiation and activated PPARγ expression, which gives a hint of the presence of adipocytes in the skeletal muscle, as can be shown for diabetes and obesity during the course of aging." (PMID 37893949, 2023). "Also associated with obesity is KDM4C located at 9p24.1, a member of the JMJD2 family that promotes preadipocyte differentiation by repressing PPARγ transcriptional activation." (PMID 37955008, 2023). "Targeting PPARγ acetylation might be promising for developing insulin sensitizers with improved safety to curb obesity, diabetes, and metabolic decline during aging." (PMID 37408258, 2023). "However, in pathologic obesity state, the function of PPARγ is dysregulated by several PTMs, which change its transactivation behavior and further aggravating obesity related metabolic disorders." (PMID 36329235, 2023). "Vitamin D‐regulating action of PPARγ on obesity has been confirmed on adipocyte differentiation." (PMID 37823117, 2023). "Our data revealed that MT3 can suppress 3T3-L1 adipocyte differentiation indirectly by inhibiting the transcriptional activity of PPARγ and by reducing ROS levels in the early stages of adipogenesis, thus providing a potential novel target for the prevention and treatment of obesity." (PMID 36978888, 2023). "Furthermore, our results showed that the molecular mechanism of Rb1 inhibiting macrophage activation was through the activation of PPARγ in the obesity microenvironment." (PMID 37049846, 2023). "Thus, potential PPARγ activators with minimal side effects are desired to accomplish the treatment of obesity and related diabetes by targeting thermogenic adipose tissue." (PMID 37435495, 2023). "The disrupted metabolic homeostasis, indicated by diminished expressions of adipogenesis-related genes such as PPARγ and Adipoq suggested that the HF-induced obesity in early life leads to adipogenesis dysfunction in iMT and potentially promotes breast tumorigenesis." (PMID 37185433, 2023). "As a result, additional study is required to understand how quercetin regulates PPARγ in obesity." (PMID 37513932, 2023). "PPARγ is recognized as acrucial therapeutic target in the management of obesity." (PMID 37886153, 2023). "A few ways BPS might be involved in the pathogenesis of obesity include PPARγ activation, prenatal exposure that potentiates high-fat diet induced weight-gain, and adipose depot- dependent effects." (PMID 37529602, 2023). "Additionally, emerging evidence suggests that both SP1 and STAT3 can suppress the expression of pivotal genes implicated in adipocyte differentiation, including PPARγ, C/EBPα, and FABP4, thereby potentially restoring insulin sensitivity and mitigating obesity." (PMID 37445596, 2023). "Interestingly, adipocyte-derived exosomes are internalized by C2C12 skeletal muscle cells and, via repression of PPARγ, seem to be related to insulin resistance induced by obesity." (PMID 36016863, 2022). "In this sense, although PPARγ is considered the “master regulator” of adipogenesis, the precise mechanism that PPARγ plays in the adipose tissue in human obesity remains unclear." (PMID 36077270, 2022).